CYP3A4 (cytochrome P450 family 3 subfamily A member 4)
Diseases named in the same sentence as CYP3A4 in open-access papers (continued):
Sharing a sentence is not in itself a finding about the gene and the disease.
hepatocellular carcinoma (58 papers, 2010 to 2026). A malignant tumor that arises from hepatocytes. "CD4, UGT2B7, and CYP3A4 were selected as the potential diagnostic biomarkers of non-alcoholic fatty liver disease–hepatocellular carcinoma." (PMID 37089050, 2023). "For example, CYP2C9, CYP2C19, and CYP3A4, which are mainly located in the liver, are diagnostic markers of hepatocellular carcinoma." (PMID 37629205, 2023). "While the expression of albumin and HNF4A remained largely unchanged in HCC-PHHs, PHCs, and HCLs (HepG2 and Huh7), CYP3A4 expression was significantly downregulated in the hepatoma cell lines." (PMID 40862732, 2025). "Further, our in vitro studies using Huh7 human hepatoma cells showed indoxyl sulfate decreases CYP3A4 expression in a concentration dependent manner." (PMID 40381485, 2025). "In this case report, we investigate a pharmacokinetic drug-drug interaction between regorafenib and sirolimus, mediated by CYP3A4 and P-gp, in a 56-year-old Chinese male with recurrent hepatocellular carcinoma post-liver transplantation." (PMID 40046750, 2025). "Conversely, patients with cirrhosis and hepatocellular carcinoma exhibit diminished hepatic CYP3A4 enzyme activity." (PMID 39957010, 2025). "Menthol increases mitochondrial membrane depolarization through TRPM8 channel leading to cell death in human bladder cancer T24 cells and enhances anti-tumor effects by downregulating cytochrome P450 3A4 (CYP3A4) in human hepatocellular carcinoma HepG2 cells." (PMID 36923503, 2023). "Licorice extract was shown to activate human pregnane X receptor (PXR) and induce CYP3A4 activity in human hepatoma cells." (PMID 37502215, 2023). "In human hepatoma cell line Hep3B, overexpression of CYP3A4 also promotes cell growth and cell cycle transition from the G1 to S phase; these effects are attenuated by a putative EET receptor antagonist: 14,15-epoxyeicosa-5(Z)-enoic acid." (PMID 36359206, 2022). "To determine if epimedium suppresses CYP3A4 mRNA expression, we conducted quantitative PCR in HepG2 cells (liver carcinoma cell line)." (PMID 36793921, 2022). "Previous studies have highlighted that most CYP members, such as CYP2C9 and CYP3A4, were defected in hepatocellular carcinoma initiation and progression." (PMID 35078445, 2022). "HepaRG cells, a human hepatocellular carcinoma cell line, is the only cell line that can differentiate into hepatocyte‐like cells with high expression of CYP3A4 but poor expression of CYP2D6." (PMID 35174659, 2022). "Our results provided a novel panel of AURKA, CDK1, TOP2A, CYP2C9, and CYP3A4 candidate genes for curcumin related chemotherapy of hepatocellular carcinoma." (PMID 35078445, 2022). "IFN-α is used to treat chronic viral infections: it suppresses CYP3A4 expression in human hepatoma cells and alter the expression of constitutive and inducible CYP3A genes in well-differentiated male rat hepatocytes in culture." (PMID 35002978, 2021). "It has also been showed that hypoxia downregulates drug-metabolizing enzymes and subsequently the chemoresistance of the HepaRG hepatoma cell line, which agrees with our findings of C3Asub28 CYP3A4 modulation under hypoxia." (PMID 34262860, 2021). "Human hepatocellular carcinoma HepaRG is the only cell line capable of providing HLCs with high CYP3A4 expression comparable to that in adult hepatocytes after cell differentiation." (PMID 32955797, 2020). "In this study we analyzed and compared the CYP3A4 inducibility of freshly isolated and cryopreserved PHHs, and human hepatoma cell lines, HepG2 and Huh7, in addition to iPSC-HHs." (PMID 32106230, 2020). "We examined the mRNA expression levels of several hepatocyte/hepatoma markers, such as albumin, ApoA1, CYP3A4, HNF4α, OATP1B3, and AFP in both cell lines and in lung carcinoma-derived A549 cells by qRT-PCR." (PMID 31138826, 2019).
hepatocellular carcinoma (continued). "Other renewable in vitro models such as HepaRG (a hepatoma-derived cell line) and Fa2N4 (an immortalized human hepatocyte cell line) have been tested as substitutes for primary human hepatocytes for modeling CYP3A4 induction DDI." (PMID 28062541, 2017). "Similar density-dependent upregulation of CYP3A4 was observed in post-confluent human hepatoma cells and in adenocarcinoma cell line Caco2-TC7, apparently due to cell adhesion triggered re-differentiation of these cells." (PMID 25844926, 2015). "Because of the great impact of CYP3A4 on efficacy and toxicity of new drugs, in vitro metabolic experiments with primary hepatocyte or hepatoma cell lines are used to assess and predict xenobiotic metabolism or toxicity at an early stage of drug development." (PMID 24788541, 2014). "In this regard, our study aimed to increase CYP3A4 expression in a commonly used human hepatoma cell line, Hep G2." (PMID 24733486, 2014). "We examined the effects of ketoconazole cis-enantiomers on the expression of CYP3A4 in two experimental in vitro systems, i.e. in human hepatoma cells HepG2 and in primary human hepatocytes." (PMID 25343516, 2014). "C3A, a hepatoma cell line, was used as the cell model to test the regulation effect of chimeric hPXR over wild type (WT) hPXR on CYP3A4 expression at gene, protein, and metabolism levels, respectively." (PMID 24788541, 2014). "Most hepatoma cell lines lack proper expression and induction of CYP3A4 enzyme, which limits their use for predicting drug metabolism and toxicity." (PMID 24788541, 2014). "Moreover, together with the loss of growth arrest, the previous enhancement of maturation in the hepatoma line was significantly reduced as shown by decreased expression of maturation markers CYP3A4, ALB, AHR, GLUL, and PCK1." (PMID 38037844, 2024). "For example, menthol has been found to reduce the resistance of human hepatocellular carcinoma HepG2 cells to the anticancer drugs paclitaxel and vincristine by inhibiting the expression of cytochrome P450 family 3 subfamily A member 4 (CYP3A4), thus preventing cancer." (PMID 37007039, 2023). "Finally, we would like to discuss the relationship between CYP3A4 enzyme and hepatoma from the viewpoint of inhibiting hepatocarcinogenesis, which is one of the biological activities of GGA." (PMID 35208214, 2022). "In summary, so far as we known, our results first showed that CDK1, TOP2A, CYP2C9, and CYP3A4 genes correlated to curcumin-related chemotherapy of hepatocellular carcinoma, more than just correlated to diagnosis and prognosis of hepatocellular carcinoma which had highlighted by the previous studies." (PMID 35078445, 2022). "On the other hand, the CYP3A4 gene is also highly expressed in the liver and is involved in maintaining the concentration of GGA when the MAOB gene is deficient, thus it is expected to have an inhibitory effect on hepatoma." (PMID 35208214, 2022). "Similarly, there is evidence that therapeutic efficacy of drugs have been diminished through CYP3A4 enzyme expressed by hepatocellular carcinoma cells." (PMID 34262860, 2021). "Our results indicate that both hepatoma originated cell lines and iPSCs may provide alternative sources to primary hepatocytes, providing reliable and reproducible results for CYP3A4/PXR metabolism, upon in vitro maturation." (PMID 32106230, 2020). "Likewise, Bmal1 knockdown led to downregulation of Cyp3a11/CYP3A4 in various hepatoma and colon carcinoma cell lines (i.e., Hepa1-6, Hepa-1c1c7, CT26, HepG2, and Caco-2)." (PMID 31633069, 2019). "For instance, certain liver-specific functions, including the metabolism by at least CYP1A2 and CYP3A4, are enhanced when cultivating hepatoma cells within three-dimensional alginate scaffolds, different co-culture systems or on PHBV microspheres to stimulate liver microarchitecture." (PMID 24788541, 2014).
hepatocellular carcinoma (continued). "To further our understanding of CYP enzymes and to advance the use of hepatoma cells as replacements for primary hepatocytes, we investigated the expression and enzyme activity of CYP3A4 in Hep G2 cells following the delivery of hepatocyte nuclear factor-1 alpha (HNF1α) using a lentivirus system." (PMID 24733486, 2014). "Moreover, it attenuated rifampin-, paclitaxel-, and SR12813-mediated CYP3A4 induction in human hepatoma and colon adenocarcinoma cells." (PMID 22645625, 2012). "CYP3A4 and CYP1A2 have been shown to be efficient in metabolizing aflatoxin B1 (AFB1), a carcinogen implicated in the etiology of hepatocellular carcinoma (HCC)." (PMID 39682707, 2024). "Hepatocellular carcinoma cell lines with higher levels of CYP3A4 exhibited an increase in DOX resistance, while those with lower levels of CYP3A4 showed a decrease in DOX resistance." (PMID 37958656, 2023). "Kratom, a native herb, which grows in Southeast Asia, can increase the protein expression of CYP3A4 and P-gp by activating PXR in human hepatocellular carcinoma (HepG2) cells." (PMID 35517807, 2022). "When hepatoma cells were treated with IL-6, the levels of CYP1A1, CYP1A2, CYP2B6, CYP3A3, and CYP3A4 mRNAs were markedly suppressed, as well as activities of CYP1A2, CYP2B6, and CYP3A4." (PMID 35185562, 2022). "There was not significant correlation between the expression of CYP2B6 and prognosis of hepatocellular carcinoma, while CYP2C9 and CYP3A4 genes were significantly downregulated and correlated with poor prognosis in hepatocellular carcinoma." (PMID 35078445, 2022). "Being a substrate of CYP3A4, sorafenib (SOR), the first-line therapy for the treatment of hepatocellular carcinoma, shows a great probability to exhibit pharmacokinetic (PK) interaction with ITs." (PMID 31871933, 2019). "Another study showed that growing placenta MSCs on a 3D fluidized bioreactor and treating them with hepatoma-derived C3A significantly improved ALB, urea secretion, and increased CYP1A2 and CYP3A4 that indicated significant differentiation of SCs into hepatocytes." (PMID 36685673, 2023). "Therefore, MAOB and CYP3A4, which are alternatively involved in the biosynthesis of hepatic GGA, are both hepatoma suppressive genes." (PMID 35208214, 2022). "When we merged these hub genes with differentially expressed genes in GSE14520 dataset and differentially expressed genes of hepatocellular carcinoma in GEPIA database, seven communal genes were found, they were AURKA, CDK1, CCNB1, TOP2A, CYP3A4, CYP2C9, and CYP2B6." (PMID 35078445, 2022). "For example, ARG1, CYP2C8, CYP3A4, CYP3A7 and CYP4A11, which we identified using MOG as decreasing expression with LIHC progression, have each been recently studied as prognostic markers for hepatocellular carcinoma." (PMID 31956905, 2020). "Similar findings have been found for CYP3A4 in Hepatocellular Carcinoma tissues as compared to paired adjacent noncancerous liver tissues." (PMID 31105885, 2019). "mRNAs of hepatocyte/hepatoma markers, such as albumin, ApoA1, CYP3A4, and AFP, were detectable in KH and Huh-7.5 cells, but not in A549 cells, indicating that KH cells, similar to Huh-7.5 cells, are derived from hepatocyte/hepatoma cells." (PMID 31138826, 2019). "In this study, we determined whether fucoxanthin may overcome drug resistance through attenuation of rifampin-induced CYP3A4 and MDR1 gene expression by PXR-mediated pathways in HepG2 hepatoma cells." (PMID 22363234, 2012). "In this study, we determined whether fucoxanthin could overcome drug resistance through attenuation of rifampin-induced CYP3A4 and MDR1 gene expression by PXR-mediated pathways in HepG2 hepatoma cells." (PMID 22363234, 2012). "Essentially identical results regarding CYP3A4 activity and expression were observed in replica experiments using GlyA-CHO or HepG2 (hepatocellular carcinoma G2 cell line) cell cultures that did not receive Chx." (PMID 41022321, 2025).
hepatocellular carcinoma (continued). "VEGF TKIs used in hepatocellular carcinoma (HCC) treatment, lenvatinib, sorafenib, regorafenib, and cabozantinib are metabolized by CYP3A4, but not all strong inducers/inhibitors have a clinical impact upon them." (PMID 40732249, 2025).
COVID-19 (53 papers, 2020 to 2025). A disease caused by infection with severe acute respiratory syndrome coronavirus 2. "This pharmacogenetics study identified deleterious point mutations in the genes encoding CYP3A4/5 enzymes involved in the metabolism of FDA/EMA-approved COVID-19 antiviral drugs, remdesivir, nirmatrelvir/ritonavir." (PMID 39819897, 2025). "In conclusion, our main findings suggest the impact of CYP3A4 rs35599367 polymorphism on the occurrence of critical COVID-19 and also on poor outcome of dexamethasone treatment." (PMID 39135792, 2024). "Our findings bring novel evidence of NR3C1 rs6198, GSTP1 rs1695, and CYP3A4 rs35599367 polymorphisms having impact on COVID-19 severity, the course of the disease, and the outcome of treatment with dexamethasone and methylprednisolone." (PMID 39135792, 2024). "It is worth mentioning that the IL-6 threshold identified in our analysis (27.9 pg/mL) is of similar extent to that (18 pg/mL) identified in a previous study carried out among COVID-19 adult patients who were associated with impaired CYP3A4-mediated darunavir clearance after CART analysis." (PMID 39065156, 2024). "Genetic variants of CYP3A4 regulating the function or expression of CYP3A4 may affect the safety or efficacy of darunavir/cobicistat in COVID-19 patients and should be considered in future studies." (PMID 35250581, 2022). "TGB, as a substrate for CYP3A4, may be susceptible to the interaction with COVID-19 vaccines due to interferon-gamma production from T-cell responses elicited by COVID-19 vaccines." (PMID 34502487, 2021). "Our study is the first randomized controlled prospective study in the literature in which MDR-1/ABCB1 and CYP3A4 gene variants that may cause changes in ivermectin dose were investigated in patients with COVID-19." (PMID 33947344, 2021). "Hence, co-administration with strong CYP3A4 inhibitors including drugs to be used in COVID-19 treatment such as Paxlovid (association of nirmatrelvir and ritonavir) may be used with caution, and dose adjustment strategies have been described." (PMID 35337177, 2022). "Thus, CYP3A4, by participating in the metabolism of vitamin D and eicosanoids, may be implicated in COVID-19 pathogenesis." (PMID 36359206, 2022). "Simnotrelvir/ritonavir was conditionally approved in January 2023 in China for the treatment of adult patients with mild-to-moderate COVID-19.Ritonavir is a potent inhibitor of CYP3A4, while simnotrelvir is a substrate of CYP3A." (PMID 41268210, 2025). "Nirmatrelvir has a desirable acute toxicity and safety profile that reinforces its position as a first-line treatment of COVID-19 despite a low oral bioavailability and dependence on CYP3A4." (PMID 41305458, 2025). "The use of the ivermectin as an alternative treatment for COVID-19 by individuals with diabetes and/or hypertension has motivated the necessity of evaluating the possible inhibition of CYP3A4." (PMID 39596155, 2024). "For example, CYP3A4 involved in the metabolism of dexamethasone, a corticosteroid drug often administered to hospitalized COVID-19 patients, is known to be dysregulated by inflammation." (PMID 37180730, 2023). "In the case of nirmatrelvir, drug exposure is significantly higher when this is co-administered with ritonavir due to CYP3A4 inhibition, enhancing the effect against COVID-19." (PMID 37368815, 2023). "Ivermectin, for instance, has been suggested to have antiviral effect against COVID-19 and is metabolized via CYP3A4, hence a 2 h delay between the administration of ivermectin and vitamin D has been advised." (PMID 36295089, 2022). "Given that many of the suggested anti-COVID-19 drug agents are activated/metabolized by CYP3A4, this highlights the importance of studying the drug interactions related to vitamin D." (PMID 36295089, 2022). "Darunavir being a substrate of CYP3A4 was used simultaneously with cobicistat, a CYP3A4 inhibitor in a clinical trial for COVID-19 for increasing the exposure of darunavir." (PMID 35250581, 2022).
COVID-19 (continued). "Because most of the repurposed drugs against COVID-19, such as lopinavir/ritonavir, are the substrates of CYP3A4." (PMID 35979235, 2022). "Given the well-known drug–drug interactions due to being a substrate for CYP2C19, CYP2C9 and CYP3A4, voriconazole interacts with COVID-19 therapy, such as remdesivir, which is also metabolized via CYP3A4." (PMID 35448646, 2022). "However, concomitant administration of statins and COVID-19 antiviral drug Paxlovid may increase statin exposure and the risk of adverse effects, because most statins are metabolized mainly through CYP3A4 which is potently inhibited by ritonavir, a major component of Paxlovid." (PMID 35811982, 2022). "It has narrow therapeutic window and drug-drug interaction with multiple other drugs including anti-COVID-19 drugs metabolized by CYP3A4." (PMID 34829179, 2021). "A recent study demonstrated that, like other viral infections, during the progression of COVID-19 local and systemic inflammation as well as the “cytokine storm” will potentially cause downregulation of the major CYP enzymes including CYP3A4." (PMID 34544500, 2021). "The adverse effects of statins coupled with their pharmacokinetic effects in the liver by hepatic isoenzymes CYP3A4 are the main reasons for the physician’s reluctance in considering statins as a supplement therapy for COVID-19 patients." (PMID 34604534, 2021). "LPV/RTV, the current first-line antiretroviral drugs for HIV treatment, presented an antiviral effect against respiratory syndrome coronavirus two and have shown efficacy in COVID-19 patients; both are metabolized by CYP3A4." (PMID 34899329, 2021). "For example, systemic corticosteroids (i.e. dexamethasone), which have been recently recommended for use in COVID-19 patients receiving supplemental oxygen, relies on CYP3A4 for metabolism." (PMID 35145560, 2021). "Regarding CYP3A4 rs35599367-rs2740574 haplotypes, TA haplotype carriers had higher odds for more severe COVID-19 (OR = 6.833; 95% CI = 1.234–37.825: p = 0.028) and for the need for ICU treatment (OR = 10.875; 95% CI = 1.877–62.992: p = 0.008), when compared to CA haplotype." (PMID 39135792, 2024). "Licorice is one of the most frequently involved herbs in these herbal formulae or preparations against COVID-19, increasing risk for HDIs for anti-COVID-19 drugs, and has been reported to modulate several CYP isoforms in vitro, including CYP3A4, CYP2C9, and CYP2E1." (PMID 37502215, 2023). "Also, despite potential benefits, there has been hesitancy in using statins for COVID-19 due to drug-drug interactions (via CYP3A4), and toxicity in the setting of liver and/or renal failure." (PMID 35991665, 2022). "Variants in CYP3A4, CYP3A5, CYP2C8, CY2D6, ABCB1, ABCC2, and SLCO1B1, among other variants, could be included in pharmacogenetic studies of COVID-19 treatment." (PMID 33807592, 2021). "Most statins are metabolized by CYP3A4 in the liver, however, in cases of simultaneous administrations of CYP3A4 inhibitors for COVID-19, such as ritonavir, it is recommended to start with lower doses of statins, while monitoring creatine kinase and transaminase levels." (PMID 34867819, 2021). "TPM is CYP3A4 inducer and may interact with anti-COVID-19 medication increasing darunavir/cobicistat and lopinavir/ritonavir concentrations." (PMID 34502487, 2021). "CYP3A4 has been reported to be the most impacted isoform in inflammation-related P450 down-regulation, which might lead to lower metabolism, prolonged half-life, and increased plasma concentration of CYP3A4 substrate drugs used for COVID-19 treatment." (PMID 34899329, 2021). "Pfizer’s Paxlovid, a combination of Nirmatrelvir and Ritonavir, is currently approved by the FDA for emergency use in the treatment of mild to moderate COVID-19 in certain adult and child patients, but it is also a potent CYP3A4 inhibitor, which could lead to drug interactions." (PMID 37368467, 2023).